EDEM2 (ER degradation enhancing alpha-mannosidase like protein 2)
Description:
Involved in the endoplasmic reticulum-associated degradation (ERAD) pathway that targets misfolded glycoproteins for degradation in an N-glycan-dependent manner. May initiate ERAD by promoting the first mannose trimming step of ERAD substrates, from Man9GlcNAc2 to Man8GlcNAc2. Seems to recognize and bind to exposed hydrophobic regions in target proteins (By similarity).
Synonyms: C20orf31; C20orf49; FLJ10783; bA4204.1
Tractability: Antibody: UniProt predicts a signal peptide or a membrane-spanning region. PROTAC: ubiquitination databases record sites on it; its protein half-life has been measured.
Gene: Protein-coding gene on chromosome 20 (35,115,360 to 35,147,358, reverse strand). Ensembl gene ENSG00000088298.
Subcellular location: Endoplasmic reticulum lumen
Pathways (Reactome):
Disease: Maturation of spike protein
Metabolism of proteins: ER Quality Control Compartment (ERQC)
Gene Ontology:
Molecular function: mannosyl-oligosaccharide 1,2-alpha-mannosidase activity; calcium ion binding
Biological process: endoplasmic reticulum mannose trimming; ERAD pathway; positive regulation of retrograde protein transport, ER to cytosol; endoplasmic reticulum unfolded protein response; trimming of terminal mannose on C branch; ubiquitin-dependent glycoprotein ERAD pathway; viral protein processing; carbohydrate metabolic process; glycoprotein metabolic process
Cellular component: endoplasmic reticulum; endoplasmic reticulum lumen; endoplasmic reticulum quality control compartment; membrane
Genetic constraint (gnomAD): Loss-of-function variants: 38 observed, 66.47 expected, observed/expected ratio (o/e) 0.57, 90% interval 0.44 to 0.75. The upper end of that interval is the gene's LOEUF score, 0.75, which puts it in group 3 of 6, group 1 being the genes least tolerant of losing a copy. Missense variants: 609 observed, 760.91 expected, observed/expected ratio (o/e) 0.8, 90% interval 0.75 to 0.86. Synonymous variants: 296 observed, 301.37 expected, observed/expected ratio (o/e) 0.98, 90% interval 0.89 to 1.08.
Homologues: Orthologues: chimpanzee EDEM2 (99% identical), macaque EDEM2 (98% identical), dog EDEM2 (96% identical), pig EDEM2 (96% identical), guinea pig EDEM2 (95% identical), rabbit EDEM2 (95% identical), rat Edem2 (94% identical), mouse Edem2 (94% identical), tropical clawed frog edem2 (75% identical), zebrafish edem2 (69% identical), Drosophila melanogaster Edem2 (36% identical), Caenorhabditis elegans ZC506.1 (35% identical), and 3 more. Paralogues in human: EDEM1 (39% identical), EDEM3 (38% identical), MAN1C1 (28% identical), MAN1A2 (27% identical), MAN1B1 (26% identical), MAN1A1 (25% identical).
Diseases named in the same sentence as EDEM2 in open-access papers:
EDEM2 is named in the same sentence as 27 diseases in open-access papers, as found by Europe PMC text mining. Sharing a sentence is not in itself a finding about the gene and the disease. The quoted sentences say what the papers report.
glioma (3 papers, 2022 to 2026). A benign or malignant brain and spinal cord tumor that arises from glial cells (astrocytes, oligodendrocytes, ependymal cells). "The frequency of mutations in the EDEM2 gene in TCGA glioma samples was very low, with 0.4% and 0.7% in LGG and GBM, respectively." (PMID 36727065, 2022). "The diagnostic and prognostic utility of EDEM2 in glioma was examined in this study using high-throughput RNA sequencing data for integrated bioinformatics analysis." (PMID 36727065, 2022). "The association of EDEM2 with extracellular matrix changes was further corroborated by the observation that EDEM2 knockdown suppressed glioma cell invasion." (PMID 36727065, 2022). "Furthermore, EDEM2 is also associated with immune infiltration in glioma and is considered a diagnostic and prognostic biomarker for the disease." (PMID 39535371, 2025). "High-grade gliomas had stronger EDEM2 expression based on immunohistochemistry, and the expression of cluster of differentiation 68 (CD68), cluster of differentiation 4 (CD4), and cluster of differentiation 8 (CD8) was higher in the samples." (PMID 36727065, 2022). "According to pertinent cohort studies using glioma single-cell transcriptome sequencing, EDEM2 was also abundantly expressed in monocytic macrophages." (PMID 36727065, 2022). "A relatively higher expression of EDEM2 was found in common cancers, and the prognostic value of EDEM2 in glioma was significantly higher than that in other cancers." (PMID 36727065, 2022). "In the glioma samples, compared to the normal tissues, the expression of EDEM2 was considerably increased (p < 0.001)." (PMID 36727065, 2022). "According to our research, EDEM2 expression is a reliable indicator of a glioma patient’s prognosis and plays a role in controlling the tumor’s immune microenvironment." (PMID 36727065, 2022). "Therefore, we gathered voluminous glioma-related data to examine the role of EDEM2 in glioma prognosis." (PMID 36727065, 2022). "Our findings imply that EDEM2 may be useful as a biomarker for the diagnosis, treatment, and prognosis of gliomas." (PMID 36727065, 2022). "The biological role of EDEM2 in glioma must be demonstrated through more experimental confirmation." (PMID 36727065, 2022). "In glioma patients, elevated EDEM2 expression was shown to be substantially related to a bad prognosis for the first time in our investigation, which suggests that it may encourage carcinogenesis through abnormal immune responses." (PMID 36727065, 2022). "According to the findings of the functional enrichment analysis of DEGs, EDEM2 may have a role to play in the control of extracellular matrix and membrane signaling in gliomas." (PMID 36727065, 2022). "Therefore, we hypothesized that by modifying the immune infiltrate in gliomas, EDEM2 would affect patient prognosis." (PMID 36727065, 2022). "Therefore, this study primarily focused on the function of EDEM2 in cases of glioma." (PMID 36727065, 2022). "Thus, EDEM2 may be used as a possible biomarker to determine a patient’s diagnosis and prognosis in cases of glioma." (PMID 36727065, 2022). "In glioma cell lines, GLA knockdown suppressed cell viability and downregulated EDEM2." (PMID 41952691, 2026). "As far as our knowledge goes, no study so far examined EDEM2 expression and its possible effects on cases of glioma." (PMID 36727065, 2022). "There was no discernible variation in the expression of EDEM2 across a range of glioma tissue grades, IDH statuses, or ages." (PMID 36727065, 2022).
melanoma (3 papers, 2021 to 2022). A malignant, usually aggressive tumor composed of atypical, neoplastic melanocytes. "In melanoma, EDEM2 has been shown to regulate integrin-1, and protocadherin 2 degradation and trafficking have been linked to melanoma metastasis and invasion." (PMID 36727065, 2022). "The aim of this study was to characterize the functional proteomic landscape of EDEM2 and define its endogenous candidate substrates in melanoma cells." (PMID 34332121, 2021). "We took advantage of using melanoma cells overexpressing EDEM2 as a cancer model system, to start documenting at the deglycoproteome level (N-glycosites identification) the emerging link between ER homeostasis and cancer progression." (PMID 34332121, 2021). "These included tumor antigens and several ER-transiting endogenous melanoma proteins, including integrin alpha-1 and protocadherin 2, the expression of which was negatively correlated with that of EDEM2." (PMID 34332121, 2021). "The EndoH deglycoproteome of EDEM2 knock-down melanoma cells is of special interest considering that this fraction includes EDEM2 endogenous substrates accumulating within the ER." (PMID 34332121, 2021). "The experiments also reveal novel potential EDEM2 endogenous substrates and characterize one of the largest endo-β-N-acetylglucosaminidase H (EndoH)–sensitive N-deglycoproteome from melanoma cells." (PMID 34332121, 2021). "To further confirm the results from the N-glycoFASP workflow, we performed a SILAC-based pulse analysis (pSILAC) of A375 melanoma cells overexpressing EDEM2." (PMID 34332121, 2021). "The AE experiments were performed from digitonin lysates of A375 melanoma cells constitutively expressing empty vector (A375-C) or HA-tagged EDEM2 (A375-E2), and the captured proteins were detected using MS." (PMID 34332121, 2021). "We find a network of ER-resident proteins that associates with EDEM2 in distinct protein complexes and describe a number of potential EDEM2 substrates involved in melanoma adhesion and progression." (PMID 34332121, 2021). "Hence, these results suggest that EDEM2 reduces ST-TYR levels in melanoma cells by targeting the substrate to the ubiquitin–proteasome degradation, and this event is dependent on the N-glycan mannose trimming in A375 melanoma cells." (PMID 34332121, 2021). "To confirm some of the identified potential substrates, we monitored the candidates, PCDH2, ITGA1, and the melanoma antigen TRP-1, expression, and intracellular distribution in A735-ST-TYR melanoma cells with either overexpressed or downregulated EDEM2 protein expression." (PMID 34332121, 2021). "EDEM2 could therefore have a regulatory role in melanoma through the modulation of degradation and trafficking in these glycoproteins." (PMID 34332121, 2021). "Thus, at least in our hands, EDEM2 is associated with members of both the ERAD pathway and the quality control system in melanoma cells." (PMID 34332121, 2021). "•Soluble tyrosinase degradation is EDEM2 dependent in melanoma cells." (PMID 34332121, 2021). "Thus, it is likely that EDEM2 has a regulatory role in melanoma metastasis and invasion through the regulation of degradation and trafficking of at least these glycoproteins." (PMID 34332121, 2021). "However, the substantiation of ST-TYR as an EDEM2 degradation substrate in two separate approaches involving either overexpression or downregulation of EDEM2 in melanoma cells validates the results of the AE proteomic approach." (PMID 34332121, 2021). "Furthermore, we used pSILAC to analyze the differential protein turnover in melanoma cells upon EDEM2 overexpression." (PMID 34332121, 2021). "Furthermore, this allowed us to use the same system to find novel endogenous candidates for EDEM2 in human melanoma cells." (PMID 34332121, 2021).
melanoma (continued). "Misfolded ERAD substrates are usually sent to degradation via a glyco-dependent ubiquitin–proteasome pathway, so we next tested whether proteasome or mannosidase inhibitors would stop the EDEM2-induced degradation of ST-TYR in A375 melanoma cells." (PMID 34332121, 2021). "Thus, considering all these results, we show here that, at least in our hands, in A375 melanoma cells, ITGA1, PCDH2, and TRP-1 are phenotypically similar with the novel EDEM2 substrate, ST-TYR." (PMID 34332121, 2021).
diabetes (2 papers, 2025). "Studies have shown that EDEM2 silencing decreases SLC2A2 and PXD1 expression, leading to impaired insulin secretion, and that it is involved in early childhood diabetes." (PMID 39535371, 2025).
breast carcinoma (1 paper, 2022). "The predicted putative marker proteins EDEM2 and IL18BP are especially interesting, because their genes were found to be significantly upregulated in all breast cancer microarrays included in the analysis." (PMID 36140706, 2022).
cardiomyopathy (1 paper, 2025). A disease of the heart muscle or myocardium proper. "Moreover, we demonstrate that EDEM2 was positively correlated with ATGL activity; therefore, metabolic stress-induced EDEM2 disruption exasperated cardiac lipotoxicity and the progression of cardiomyopathy, at least partially, via impaired ATGL translocation in cardiomyocytes." (PMID 40130322, 2025).
malaria (1 paper, 2014). Malaria is a serious and sometimes fatal disease caused by a parasite that commonly infects a certain type of mosquito which feeds on humans. "Because EDEM2 does not appear to be involved in malaria pathogenesis, the six EDEM2 SNPs would not be primarily associated with severe malaria." (PMID 24635948, 2014).
mastitis (1 paper, 2024). Inflammation of breast tissue during lactation or postpartum due to an obstructed duct or infection. "The targeted genes, PLIN3, EDEM2, SURF4, and LGALS9, with mutations/variations have led to metabolic diseases, bovine osteoporosis, mastitis resistance and bovine respiratory disease, respectively." (PMID 38674383, 2024).
periodontitis (1 paper, 2022). An acute or chronic inflammatory process that affects the tissues that surround and support the teeth. "In our study, SERPINA1 was the core gene in PPI and correlated with seven ERS-related genes including ERLEC1, VWF, EDEM2, DERL3, APOE, IL6, and CXCL8, suggesting that SERPINA1 may play an essential role in the pathological process of periodontitis." (PMID 36072904, 2022).
prostate adenocarcinoma (1 paper, 2022). "We treated LNCaP (prostate adenocarcinoma cells) and RWPE-1 cells (normal prostatic epithelial cells) with 10 nM synthetic androgens (R1881) for 24 h and assessed gene expression of EDEM1, EDEM2 and EDEM3." (PMID 35897761, 2022). "We first looked in The Cancer Genome Atlas (TCGA) prostate adenocarcinoma (PRAD) Firehose cohort to compare EDEM1, EDEM2 and EDEM3 gene expression data in prostate adenocarcinoma tissue (n = 497) and normal prostate tissue (n = 52)." (PMID 35897761, 2022).
prostate carcinoma (1 paper, 2022). A carcinoma that arises from epithelial cells of the prostate gland. "In contrast, neither EDEM1 nor EDEM2 gene expression correlated with disease-free survival in prostate cancer patients." (PMID 35897761, 2022). "EDEM1 and EDEM2 were slightly increased in prostate cancer patients in two out of five cohorts, suggesting that they may play some role in ERAD in prostate cancer; however, their expression was in no way associated with disease-free progression." (PMID 35897761, 2022).
renal carcinoma (1 paper, 2025). A carcinoma arising from the epithelium of the renal parenchyma or the renal pelvis. "Similarly, analysis of the Human Protein Atlas (HPA) reveals unfavourable prognoses in renal cancers overexpressing EDEM2 and EDEM3." (PMID 39838427, 2025).
sarcopenia (1 paper, 2025). Progressive decline in muscle mass due to aging which results in decreased functional capacity of muscles. "Although the role of these genes in sarcopenia and muscle function has not been studied, some of them such as AS3MT and EDEM2 have been reported to affect brain function and development." (PMID 39535371, 2025).
schizophrenia (1 paper, 2020). A major psychotic disorder characterized by abnormalities in the perception or expression of reality. "Moreover, increased expression levels of proteins associated with recognizing and modifying misfolded proteins, including HUGT2 and ER degradation-enhancing alpha-mannosidase-like protein 2 (EDEM2) but not HUGT1 were found in dorsolateral prefrontal brain cortex in schizophrenia." (PMID 31796523, 2020).
type 2 diabetes (1 paper, 2021). "Transcription factors co-regulating the pancreatic expression of EDEM2, MYH7B, MAP1LC3A, and CPNE1 genes that associated with type 2 diabetes have been predicted by the hTFtarget tool." (PMID 34575035, 2021). "Thus, the TWAS analysis allowed revealing the genetic association between the changes in pancreatic expression of genes such as EDEM2, MYH7B, MAP1LC3A, and CPNE1 and the risk of type 2 diabetes." (PMID 34575035, 2021). "In addition, further TWAS analysis has revealed that the increased pancreatic expression of EDEM2, MYH7B, MAP1LC3A and decreased levels of CPNE1 are associated with the genetic risk of type 2 diabetes." (PMID 34575035, 2021). "The TWAS analysis has shown that the pancreatic expression of EDEM2, MYH7B, MAP1LC3A, and CPNE1 correlated to a carriage of T2D-associated alleles of GSS and GGT7 is associated with the genetic risk of type 2 diabetes." (PMID 34575035, 2021).
cancer (5 papers, 2018 to 2024). A tumor composed of atypical neoplastic, often pleomorphic cells that invade other tissues. "t10,c12 CLA decreased the expression of Hsp90 and EDEM2, suggesting that t10,c12 CLA interferes with ERAD and thereby locks the cancer cells in a persistent state of ER stress.." (PMID 29324748, 2018).
tumor (3 papers, 2017 to 2022). "In contrast to normal samples, we discovered that the expression of EDEM2 was greater in tumor tissues." (PMID 36727065, 2022). "To validate our findings regarding CNVs identified by CNVpanelizer, we investigated SOX11, CDX2, MMP9, CARD11 and EDEM2 copy numbers in 41 tumour sections by gene-specific FISH." (PMID 28120820, 2017). "Furthermore, high-grade, IDH wild-type, and 1p/19q non-coding tumor tissues had significant levels of EDEM2 expression." (PMID 36727065, 2022). "However, the specific molecular link between EDEM2 and the UPR within the tumor microenvironment (TME) remains unexplained." (PMID 36727065, 2022).
metabolic disease (2 papers, 2024 to 2025). A congenital disorder (due to inherited enzyme abnormality) or acquired (due to failure of a metabolically important organ) disorder resulting from an abnormal metabolic process. "Conversely, EDEM2 overexpression alleviated the deleterious effects, shielding the heart from metabolic disorder–induced insult, particularly in XBP1s deficiency–induced HFpEF hearts." (PMID 40130322, 2025).
Cardiovascular Disease (1 paper, 2025). "Analysis using the Cardiovascular Disease Knowledge Portal provided genetic evidence supporting the involvement of EDEM2 in cardiovascular diseases and lipid regulation." (PMID 40130322, 2025).
EDEM2 also shares sentences with these, for which no sentence is quoted: bipolar disorder (1 paper); cardiac hypertrophy (1); Chagas disease (1); colon tumour (1); Hepatitis C (1); hereditary angioneurotic edema (1); hyperprolinemia type 2 (1); major depression (1); Obesity (1).